RAB40AL (RAB40A like)
Description:
May act as substrate-recognition component of the ECS(RAB40) E3 ubiquitin ligase complex which mediates the ubiquitination and subsequent proteasomal degradation of target proteins (By similarity). The Rab40 subfamily belongs to the Rab family that are key regulators of intracellular membrane trafficking, from the formation of transport vesicles to their fusion with membranes. Rabs cycle between an inactive GDP-bound form and an active GTP-bound form that is able to recruit to membranes different sets of downstream effectors directly responsible for vesicle formation, movement, tethering and fusion (By similarity).
Synonyms: RLGP; RAR2; MRXSMP
Tractability: Antibody: its Gene Ontology location is reachable by antibodies, with medium confidence. PROTAC: ubiquitination databases record sites on it.
Gene: Protein-coding gene on chromosome X (102,937,272 to 102,938,300, forward strand). Ensembl gene ENSG00000102128.
Subcellular location: Membrane; Cytoplasm; Mitochondrion
Subcellular location (Human Protein Atlas): Vesicles
Gene Ontology:
Molecular function: GTPase activity; G protein activity; GTP binding
Biological process: exocytosis; intracellular signal transduction; protein ubiquitination
Cellular component: cytoplasm; mitochondrion; endosome; plasma membrane; synaptic vesicle; membrane
Gene-disease validity (ClinGen):
ClinGen rates the evidence that RAB40AL causes each of these diseases.
X-linked syndromic intellectual disability (X-linked): Refuted.
Homologues: Orthologues: macaque RAB40AL (99% identical). Paralogues in human: RAB40A (98% identical), RAB40B (88% identical), RAB40C (75% identical), RAB10 (28% identical), RAB8A (28% identical), RAB1A (27% identical), RAB1B (27% identical), RAB6A (27% identical), RAB13 (27% identical), RAB15 (27% identical), RAB8B (27% identical), RAB6B (27% identical), and 56 more.
Diseases named in the same sentence as RAB40AL in open-access papers:
RAB40AL is named in the same sentence as 1 disease in open-access papers, as found by Europe PMC text mining. Sharing a sentence is not in itself a finding about the gene and the disease. The quoted sentences say what the papers report.
lung carcinoma (1 paper, 2025). "However, it is interesting to note that RAB40AL, a closely related isoform of RAB40A, is linked to Martin-Probst Syndrome and lung cancer cell migration." (PMID 39736966, 2025).